SDC1 (syndecan 1)
Diseases named in the same sentence as SDC1 in open-access papers (continued):
Sharing a sentence is not in itself a finding about the gene and the disease.
mesothelioma (continued). "Among mesothelioma patients with serum syndecan-1 levels higher than the median (144 ng/mL), the median survival time was 9.0 months, while in those with lower serum levels, it was 11.0 months; however, this difference was not statistically significant (hazard ratio 1.43, 95% CI 0.63 to 3.98)." (PMID 25147801, 2014). "Syndecan-1 levels were also higher in effusions from patients with mesothelioma." (PMID 25147801, 2014). "Overexpression of syndecan-1 resulted in a downregulation of syndecan-2 and upregulation of syndecan-4 in epithelioid mesothelioma cells, whereas in epithelioid fibrosarcoma cell line syndecan-2 was upregulated, and in a sarcomatoid fibrosarcoma cell line syndecan-4 was downregulated." (PMID 24392351, 2013). "In addition, others found in STAV-AB mesothelioma cells that transfection of syndecan-1– contrary to the case in HT-1080– downregulates syndecan-2 expression." (PMID 22745764, 2012). "In the mesothelioma cells we could detect a nuclear pool of syndecan-1 and FGF-2, whereas FGFR-1 remained exclusively perinuclear." (PMID 19802384, 2009). "Moreover, SDC1 expression was associated with longer overall survival in patients with mesotheliomas compared to patients with no or low SDC1 expression." (PMID 26293675, 2015). "In order to investigate the role of shed SDC-1 on the tube formation of endothelial cells, we silenced MMP-7 in mesothelioma cells." (PMID 33562126, 2021). "Syndecan-1 (CD138), a cell surface proteoglycan, has been proposed as a cellular marker for distinguishing adenocarcinoma from mesothelioma." (PMID 25147801, 2014). "This is particularly interesting in the light of our previous report where exposure of mesothelioma cells to EGF and IGF-1 inhibited expression of syndecan-1 and -2." (PMID 23144729, 2012). "SDC gene was overexpressed, but its protein Syndecan-1 (CD138) an important protein related to the mesothelioma phenotype did not change either." (PMID 22905093, 2012). "In mesothelioma cells, among the angiogenesis-related proteins, angiopoietin-1, thrombospondin-1 (TSP-1), and tissue inhibitor of metalloproteinases-1 (TIMP-1) were significantly downregulated upon SDC-1 over-expression, whereas IL-8 was upregulated upon SDC-1 silencing." (PMID 33562126, 2021).
diabetes (20 papers, 2013 to 2026). "There are also other sources of SDC-1 in the body besides the endothelium such as plasma cells, and various chronic diseases such as diabetes are associated with higher baseline levels of SDC-1." (PMID 40643821, 2025). "In addition, asymptomatic patients were with older age and more diabetes, which promoting the shedding of EG and making up for the elevation of syndecan-1 caused by uncomfortable symptoms." (PMID 36158787, 2022). "We next measured circulating syndecan-1 in Cohort 2—women attending the Manchester Antenatal Vascular Service (MAViS clinic, in the United Kingdom) who have underlying vascular disease (such as chronic hypertension or pre-existing diabetes)." (PMID 34400721, 2021). "Thus, in accordance with previous studies reporting that shock and hyperglycemia/diabetes are associated with glycocalyx damage, shock and diabetes were independently associated with circulating syndecan-1 in the present study." (PMID 23433357, 2013). "For log-syndecan-1, age, gender, patient group, eGFR, SBP, diabetes, log-IS and log-PCS demonstrated significant associations, with ‘patient group’ having the greatest influence (R2 = 0.41)." (PMID 33423673, 2021). "Other glycocalyx components, including SDC1 concentration, have already been reported to be increased in serum from subjects with type 1 diabetes mellitus and microalbuminuria." (PMID 32037077, 2020). "Additionally, CXCL13, CA6, SDC1, and PTN demonstrated mediating effects in the association between Health Behaviors and outcomes such as diabetes, renal disease, and death." (PMID 41290610, 2025). "It has been reported that syndecan-1 was significantly elevated in patients with diabetes." (PMID 36158787, 2022). "CXCL13, CA6, SDC1, and PTN, on the other hand, mediate the relationship between Health Behaviors and renal diseases, diabetes, and death." (PMID 41290610, 2025). "Lower levels of SDC1 and Sirt7 were noted in the glomeruli of both DKD patients and diabetes‐induced renal injury rats, as well as in human glomerular endothelial cells (HGECs) with high blood sugar." (PMID 38686489, 2024). "Increased serum levels of ANGPTL-4, syndecan-1, PIGF, and IL-8 were observed in diabetes patients with complications." (PMID 34650995, 2021). "In our study, the shedding of the glycocalyx, syndecan-1, differed significantly between patients with and without diabetes among the enrolled patients and between patients grouped according to the median age, which was consistent with previous studies." (PMID 36158787, 2022). "Sdc4 mRNA expression was upregulated 2.5-fold, whereas Sdc1 mRNA expression was not significantly changed in diabetes." (PMID 32037077, 2020). "Although SDC1 has been extensively studied for its shedding and use as a biomarker for several diseases, shedding of SDC4 has been previously shown as an important regulator in pathologies such as cardiac dysfunctions, diabetes mellitus, osteoarthritis, and cancer." (PMID 39764382, 2024). "Similarly, SDC4 expression by enzyme-linked immunosorbent assay (ELISA) was reduced 1.6-fold in diabetic glomeruli, suggesting glomerular SDC4 shedding, whereas SDC1 glomerular protein expression was not changed in diabetes." (PMID 32037077, 2020).
cervical carcinoma (18 papers, 2015 to 2025). A carcinoma arising from either the exocervical squamous epithelium or the endocervical glandular epithelium. "In cervical cancer, SDC1 expression is associated with low differentiation and increased lymph node metastases." (PMID 39869563, 2025). "In conclusion, in cervical cancer Sdc-1 modulates pathogenetically relevant processes, which depend on the membrane-association of Sdc-1." (PMID 35155241, 2022). "The loss of Sdc-1 expression is associated with low differentiation of cervical carcinoma and with an increased rate of lymph node metastases." (PMID 35155241, 2022). "The extent of membrane syndecan-1 loss correlates with the grade of cervical cancers and also presumably with the presence of lymph node metastasis, without showing correspondence with other main clinical parameters." (PMID 32388727, 2020). "Most cervical cancer tissues assessed to date have been shown to be SDC1-positive, and localization of SDC1 in the cytoplasm was associated with better patient survival." (PMID 26293675, 2015). "Furthermore, only four genes (CXCL2, SDC1, has-miR-221-3p, and has-miR-222-3p) were associated with OS in cervical cancer." (PMID 36591476, 2022). "Given the pivotal role of SDC1 in cervical cancer, we developed a prognostic model for CC based on the C0 subtype." (PMID 40616092, 2025). "In this study, we analyzed the dysregulation and prognostic impact of Sdc-1 expression in clinical specimens of cervical cancer utilizing publically available transcriptomic datasets." (PMID 35155241, 2022). "In a different study, from 121 samples of cervical cancer, 101 (83.5%) were positive for Sdc-1 being the histological type, and grade those that showed statistical significance with Sdc-1 expression." (PMID 35155241, 2022). "Recombinant Syndecan 1 (SDC1) and CXCL10 were the two predicted genes and analysis of published works revealed that there were many reports of SDC1 in cervical cancer." (PMID 36207693, 2022). "Then, we analyzed the role of Sdc-1 in the proliferation, cell cycle, migration, and invasion characteristics of the well-established cervical cancer cell model line HeLa." (PMID 35155241, 2022). "Overall, these data confirm previous evidence for a dysregulation of Sdc-1 expression in cervical cancer, and provide novel evidence for its utility as a prognostic marker in mRNA-based analyses." (PMID 35155241, 2022). "In cervical cancer, the presence of Syndecan-1 (SDC1) in the cytoplasm of tumor cells predicts improved patient survival." (PMID 36591476, 2022). "This suggests that in cervical cancer cells, the soluble form of Sdc-1 has different downstream targets." (PMID 35155241, 2022). "In our study, we found that Sdc-1 mRNA showed a trend for a higher expression in local tumor tissues than in normal and metastatic cervical cancer tissues, and a significant correlation with poor survival of cervical carcinoma patients." (PMID 35155241, 2022). "Previously published evidence suggested a possible connection between the expression of the membrane-bound heparan sulfate proteoglycan syndecan-1 (Sdc-1) and the development of cervical carcinoma." (PMID 35155241, 2022). "This suggests that the Sdc-1-dependent changes in migration of cervical cancer cells depend on the Rho signaling pathway." (PMID 35155241, 2022). "In conclusion, In HeLa cervical cancer cells, membrane-bound and soluble forms of Sdc-1 modulate cell proliferation, apoptosis, motility, and invasiveness." (PMID 35155241, 2022). "In clinical specimens, Sdc-1 mRNA was more highly expressed in local tumor tissues than in normal and metastatic cervical cancer tissues." (PMID 35155241, 2022). "Despite all this evidence, little is known about how Sdc-1 affects the progression of cervical cancer." (PMID 35155241, 2022). "Immunohistochemistry for syndecan-1 extracellular domain was performed on surgical specimens of primary cervical cancer." (PMID 32388727, 2020).
cervical carcinoma (continued). "In the presented work the question was addressed if changes in syndecan-1 expression are related to the prognosis of cervical cancer." (PMID 32388727, 2020). "Aberrant, tumor-induced stromal expression of syndecan-1 both in squamous cell and adenocarcinomas, as recorded in our specimens, is a novel finding in cervical cancer." (PMID 32388727, 2020). "The intensity of stromal syndecan-1 immunostaining was 7.3-fold higher (Mann Whitney test: p < 0.0001) in cervical cancer than in normal tissues." (PMID 32388727, 2020). "Independent of the ultimate clinical outcome, our immunohistochemical and immunocytochemical observations confirmed that tumor-induced stromal syndecan-1 expression is a common event in human carcinomas, including cervical cancers." (PMID 32388727, 2020). "Here, we investigated the significance of pathological syndecan-1 expression and localization in cervical cancers and correlated syndecan-1 presence with the 15-year survival rate." (PMID 32388727, 2020). "In support of earlier reports, we observed serious abnormalities in the expression of syndecan-1 in invasive cervical cancers." (PMID 32388727, 2020). "Now, our culture models confirmed that syndecan-1 expression by stromal cells is a typical feature of fibroblasts isolated from cervical cancers." (PMID 32388727, 2020). "In fact, the presence of syndecan-1 is a typical feature of fibroblasts isolated from cervical cancers (unpublished result of the authors)." (PMID 25885552, 2015). "High SDC1 expression in cervical cancer is also correlated with a poor prognosis." (PMID 39869563, 2025). "In cervical cancer, high levels of syndecan-1 predict good prognosis." (PMID 39695102, 2024). "Understanding the mechanisms by which Sdc-1 promotes these processes could help to better understand the behavior of cervical cancer and find specific therapeutic targets." (PMID 35155241, 2022). "Importantly, an inverse correlation between the expression of Sdc-1 in the primary site and lymph node metastasis was observed, suggesting that Sdc-1 has a different role in the different stages of development of cervical cancer." (PMID 35155241, 2022). "Understanding the mechanisms by which different forms of Sdc-1 promote these processes could help to better understand the behavior of cervical cancer cells and to find specific therapeutic targets." (PMID 35155241, 2022). "Previous studies have indicated a dysregulation of Sdc-1 expression in cervical carcinoma tissues." (PMID 35155241, 2022). "To know more about the role of Sdc-1 in processes associated with malignancy, we analyzed the effect of the overexpression of Sdc-1 and its membrane-bound and soluble form on the malignant properties of the human cervical carcinoma cell line HeLa through functional analysis." (PMID 35155241, 2022). "Furthermore, future studies could address if Sdc-1 can function as a co-receptor for Human Papilloma Viruses as an important pathogenetic mechanism in cervical cancer." (PMID 35155241, 2022). "Therefore, reduced cell motility in Sdc-1 expressing cervical carcinoma cells may contribute to a reduction in metastatic behaviour." (PMID 35155241, 2022). "To investigate if Sdc-1 in its different forms influences the expression of invasion-related factors, we analyzed the expression levels of E-cad, MMP2, and tissue inhibitor of metalloproteinases 1 (TIMP-1), which are also associated with the metastasis of cervical cancer cells by qRT-PCR." (PMID 35155241, 2022). "Syndecan 1, a transmembrane heparan sulfate cell surface proteoglycan that is highly expressed in the normal cervical epithelium (except for the basal cell layer), presents a marked downregulation in invasive cervical carcinomas when compared with CIN samples 36,70,71." (PMID 30208169, 2018). "In addition, the change of SDC1 expression in cervical cancers was not caused by copy number alteration of the gene." (PMID 26293675, 2015).
cervical carcinoma (continued). "The upregulated ligand receptor pairs in the cervical cancer group were SPP1 − CD44, FN1 − SDC4, FN1 − SDC1, FN1 − CD44, CD99 − CD99, and the downregulated ligand receptor pairs were PPIA – BSG, LGALS9 − P4HB, LGALS9 − CD44." (PMID 41384115, 2025).
atherosclerosis (17 papers, 2014 to 2025). A disease characterized by the build-up of fatty material and calcium deposition in the arterial wall resulting in partial or complete occlusion of the arterial lumen. "This study highlights the significance of syndecan-1 in plaque vulnerability and provides valuable insights into the formation of high-risk vulnerable plaques in atherosclerosis." (PMID 39175877, 2024). "Our findings underscore the importance of serum SDC1 in plaque vulnerability, and the modified vulnerability index presents a viable tool for assessing high-risk plaques in atherosclerosis." (PMID 39175877, 2024). "In particular, macrophages derived from Sdc1 knock-out mice have reduced motility of M2-resolving macrophages, which is associated with increased atherosclerosis development in Apoe–/–Sdc1–/– mice fed a Western-type diet." (PMID 32508807, 2020). "Correlation analysis showed a negative relationship between serum syndecan-1 levels and cIMT, while regression analysis suggested that lower syndecan-1 levels in patients with Behçet’s disease might be associated with subclinical atherosclerosis." (PMID 41578772, 2025). "The expression of syndecan-1 even in early lesions may render reasonable its inclusion in some currently available risk scores or even as a marker of subclinical atherosclerosis." (PMID 37109427, 2023). "This study aimed to assess the potential of syndecan-1 levels as a biomarker for diagnosing cardiovascular diseases and atherosclerosis in patients with Behçet’s disease." (PMID 41578772, 2025). "This study aimed to investigate SDC-1 expression and its potential correlation with plaque vulnerability in ApoE−/− atherosclerosis mouse model." (PMID 39175877, 2024). "SDC1 has immunomodulatory properties, modulating motility and resolution responses of macrophages relevant to plaque destabilization in atherosclerosis." (PMID 38791454, 2024). "This study enhances our understanding of plaque vulnerability mechanisms and presents SDC1 as a potential biomarker for atherosclerosis." (PMID 39175877, 2024). "In spite of the role of syndecan-1 in EG, the value of syndecan-1 as biomarker of ED and atherosclerosis is still uncertain." (PMID 34242246, 2021). "Regarding PGs, it is postulated that their expression in atherosclerosis depends on the balance between the expressions of syndecan-1 and syndecan-4." (PMID 33997316, 2021). "Although these data have been observed in the context of atherosclerosis, it is likely that macrophage-expressed SDC1 impacts other metabolic complications such as obesity-induced diabetes." (PMID 32508807, 2020). "Syndecan-1 levels were higher in patients with Behçet’s disease compared to controls, and increased syndecan-1 may slow the progression of subclinical atherosclerosis." (PMID 41578772, 2025). "Therefore, the role of syndecan-1 in atherosclerosis and its part in the etiology of autoimmune diseases should be clarified through large-scale, randomized, controlled population studies." (PMID 41578772, 2025). "Treatments like immunosuppressive agents, TNF-α blockers, corticosteroids, and colchicine could influence the rate of atherosclerosis and syndecan-1 levels." (PMID 41578772, 2025). "Therefore, this study aimed to measure syndecan-1 levels in individuals diagnosed with Behçet’s disease and to examine its relationship with subclinical atherosclerosis." (PMID 41578772, 2025). "However, the simultaneous elevation of both serum S1P and SDC1 challenges the role of S1P in atherosclerosis." (PMID 39175877, 2024). "Moreover, syndecan-1 contributes to the pathogenesis of ischemic HF, playing an important role in the development of atherosclerosis." (PMID 37109427, 2023). "For example, if the increase in the expression of syndecan-1 is lower than that in the expression of syndecan-4 in neointimal smooth muscle cells, atherosclerosis progression influenced by the imbalance between the expressions of syndecan-1-syndecan-4 can be accelerated." (PMID 33997316, 2021).